ADNP (activity dependent neuroprotector homeobox)
Diseases named in the same sentence as ADNP in open-access papers (continued):
Sharing a sentence is not in itself a finding about the gene and the disease.
cancer (continued). "According to the vitro experiments, we speculated ADNP might be a gene related to cancer stem cells, we will conduct related experiments to verify this conjecture in the future." (PMID 37525242, 2023). "Recently, exploring the character of ADNP in cancers has become a research hotspot." (PMID 37525242, 2023). "We speculated that ADNP might facilitate the carcinoma progression and immune invasion by regulating coagulation cascades activity." (PMID 37525242, 2023). "ADNP may be a novel molecular target for predicting prognosis and cancer therapy in patients with BC after chemotherapy." (PMID 34335928, 2021). "However, the activation of ADNP signaling system, mediated by an endogenous pituitary adenylate cyclase-activating polypeptide, can increase the resistance of malignant peripheral nerve sheath tumor to H2O2-induced death with serum starvation." (PMID 34335928, 2021). "ADNP is a Homeobox transcription regulator which includes nine zinc-fingers that play a role in neuroprotective responses to cellular growth, chromatin remodelling, microtubule/autophagy regulation and cancer cell proliferation [9,]." (PMID 31767542, 2019). "ADNP may influence cancer cell migration through the TGF-β /Smad signalling." (PMID 39480826, 2024). "Our findings point to a specific role for ADNP-mediated R-loop resolution in physiological and pathological neuronal function and, more broadly, to a role for zinc finger and homeodomain proteins in R-loop regulation, with important implications for developmental disorders and cancers." (PMID 35013239, 2022). "By analyzing interactions with the GNPDA1 protein using the STRING database, researchers identified 4 key genes (GABPB1, CDK4, ADNP, and APH1A) that play important roles in cellular processes related to cancer." (PMID 40419932, 2025). "The epigenetic mechanisms by which ADNP chromatinopathies contribute to pleiotropic clinical presentations of ASD, cancer, and neurodegeneration still remain poorly understood." (PMID 36945042, 2023). "Comparing the homologous normal tissues with carcinoma tissues in HCC and COAD, the IHC results intuitively revealed a significant upregulation of ADNP protein expression." (PMID 37525242, 2023). "Future research into the biochemical logic of this normal ontogenetic neurodevelopmental process versus pathological conditions such as metastasis–carcinogenesis will further improve our understanding of the paradoxical pathophysiological roles of ADNP in ASD and cancer metastasis." (PMID 36945042, 2023). "In that respect, it is relevant to mention that ADNP was recently identified as a binding partner of the ZEB1/NuRD complex (zinc finger E-box-binding homeobox 1/Nucleosome Remodeling and Deacetylase) which is critically involved in epigenetic cancer programming of EMT hallmarks." (PMID 36945042, 2023). "As a result, the role of ADNP in cancer, or HGSOC specifically, has not been extensively studied." (PMID 31767542, 2019).
tumor (14 papers, 2011 to 2025). "ADNP expression is required for cell viability and strongly associated with tumor maturation by impacting on cell cycle progression and proliferation pathway." (PMID 36945042, 2023). "Cox regression survival analysis revealed that patients with high ADNP expression closely linked to shorter tumor-free survival." (PMID 34335928, 2021). "Go enrichment analysis showed ADNP-related DEGs may participate in detoxification of copper ions and the stress response to copper ions related with various signaling pathways and tumor associated biological behaviors." (PMID 37525242, 2023). "Besides, ADNP gene is also closely linked with tumor cells proliferation, invasion as well as migration." (PMID 34335928, 2021). "ADNP expression in HGSOC tumours is strongly associated with altered cell cycle progression and altered cell cycle checkpoints and these relationships are confirmed by analyses of down-regulated genes following ADNP silencing." (PMID 31767542, 2019). "In such context, silencing of ADNP primarily affected Wnt-signaling genes by increasing the expression of many of its effectors such as the tumor drivers DNMT1 and TALIN-1, thus showing an ADNP-mediated repression on the Wnt axis." (PMID 36945042, 2023). "We further displayed the ADNP expression differences between the tumor and normal tissues in CHOL, ESCA, GBM, LGG, PAAD, and STAD using GEPIA database." (PMID 37525242, 2023). "Our results showed that the expression of ADNP mRNA and protein were significantly upregulated in BC tissues of the patients who suffered tumor-progression via RT-PCR and western blot." (PMID 34335928, 2021). "Using immunohistochemistry on isolated nude mouse tumor tissues, the results confirmed that ADNP knockdown significantly down-regulated the expression of ADNP, N-Cadherin, and Vimentin after cisplatin intervention, while E-Cadherin expression was the opposite." (PMID 34335928, 2021). "We found the evidence in our study that ADNP can significantly promote tumor cell growth and proliferation." (PMID 33240802, 2020). "Our analyses identified increased DNA copy number gains and higher mRNA and protein expression of the transcription factor ADNP (Activity Dependent Neuroprotector Homeobox) in poorly prognostic HGSOC tumours." (PMID 31767542, 2019). "These analyses identified DNA amplification and overexpression of the transcription factor ADNP (Activity Dependent Neuroprotector Homeobox) in poorly prognostic tumours." (PMID 31767542, 2019). "Collectively, these analyses suggest that ADNP is associated with cell cycle progression and proliferation in HGSOC tumours." (PMID 31767542, 2019). "Our integrative in silico analyses of HGSOC tumour DNA copy number, mRNA and proteomic data identified ADNP as a potential novel driver of HGSOC tumorigenesis based on the association between poor prognosis and the expression of this gene/protein." (PMID 31767542, 2019). "Two of the candidates, WWC1-ADRBK2 in HCC3153 cell line and ADNP-C20orf132 in a primary tumor, were confirmed by Sanger sequencing and RT-PCR." (PMID 22032724, 2011). "ADNP might play an oncogene and immunosuppression role in tumor immune infiltration and response, thus influencing the prognosis." (PMID 37525242, 2023). "This indicated that ADNP is significantly related to tumor development and might be a potential prognostic biomarker for HCC." (PMID 37525242, 2023). "Synthesizing all analyses, we drew a conclusion that ADNP might play an immune-evasive role in the tumor microenvironment (TME)." (PMID 37525242, 2023). "ADNP knockdown inhibited tumor formation and higher drug response rate." (PMID 34335928, 2021). "Additionally, the immunohistochemistry of 128 BC tissues showed that ADNP protein was also significantly overexpressed in patients with tumor-progression (P <0.01)." (PMID 34335928, 2021).
tumor (continued). "Importantly, ADNP mRNA expression was strongly associated with both DNA CN status (p = 4.1 × 10−36) and protein expression (p = 5.1 × 10−16) indicating that this is not a silent amplification and that ADNP over-expression may be functionally relevant in this subset of tumours." (PMID 31767542, 2019). "How ADNP abrogates this process, the identification of co-factors required for ADNP activity, the down-stream signalling network activated by ADNP in HGSOC as well as other tumour characteristics impacted by ADNP overexpression remain unclear." (PMID 31767542, 2019). "However, the role of ADNP in the regulation of tumor immune response, development, and treatment resistance in HCC remains unknown and is worth exploring." (PMID 37525242, 2023). "Hence, we speculated ADNP might function as an oncogene in tumor immunosuppression via regulating coagulation cascades pathways especially in HCC." (PMID 37525242, 2023). "We found that ADNP expression was significantly correlated with high pathological grade and advanced clinical stage, indicating that ADNP may be an oncogene of BC that can lead to tumor cell proliferation and tumorigenesis." (PMID 33240802, 2020). "On the other hand, FIH-1, ADNP, and STAT1 appear to be critical in the activation of HIF and angiogenesis-related genes, under hypoxia, acting as tumor suppressors in GBM." (PMID 39055895, 2024). "Results in our study revealed that ADNP acted as an oncogene and was significantly positively correlated with CAFs, endothelial cells, MDSC, Tregs, and neutrophils with roles in promoting tumor progression and suppressing antitumor immune effects on HCC." (PMID 37525242, 2023). "For example, the AP events of several tumor-related genes, such as TRIM7, MLK4, ADNP, and TRAP1, had higher inclusion levels in G1." (PMID 35989380, 2022). "Results confirmed that BLCAP, EML1, FOSL2, ADNP and FRMD3 were deregulated in the same way among the xenografts, FFPE and OCT tumour samples." (PMID 30592148, 2019). "ADNP, an intracellular astrocyte-derived neurotrophic factor that is essential for brain development, was recently found to be expressed in hypoxic areas of GBM modulating the hypoxic-angiogenic pathway by reducing VEGF secretion, acting as a tumor suppressor." (PMID 39055895, 2024). "In the lack of growth-stimulating factors typical of MPSNT niche, the higher endogenous level of PACAP induces the overexpression of ADNP, which in turn provides a protection against H2O2-induced oxidative stress, thus mediating an adaptive mechanism that contributes to tumor cell resistance." (PMID 36945042, 2023). "The expression of ADNP mRNA was up-regulated in the patients who suffered tumor-progression versus in the patients with no-progression (P<0.05)." (PMID 34335928, 2021). "This revealed that tumor cells in MBMs not only exhibited significantly upregulated tumorigenesis and maintenance genes (e.g., MET and TBX2), but also expressed neural differentiation markers (e.g., NRG3, NELL1, NCAM1, ADNP) and cell adhesion molecules (e.g., CDH1, PRKCA)." (PMID 41284647, 2025).
neurodevelopmental disorder (12 papers, 2021 to 2025). A behavioral and cognitive disorder with onset during the developmental period that involves impaired or aberrant development of intellectual, motor, or social functions. "Other highly enriched genes for nsDNV—KMT2D (OMIM 147920), KMT2A (OMIM 605130), NSD1 (OMIM 117550), TAB2 (OMIM 614980), and ADNP (OMIM 615873)—have been previously associated with different types of neurodevelopmental disorders with co-occurrence of CHD." (PMID 34324492, 2021). "We further demonstrate that POGZ forms a nuclear complex and co-occupies loci with ADNP, another high-confidence ASD risk gene, and provide evidence that POGZ regulates other neurodevelopmental disorder risk genes as well." (PMID 34879283, 2021). "Also, we have identified 15 de novo variants in genes that were previously implicated in ASD or related neurodevelopmental disorders (PHF21A, WASF1, TCF20, DEAF1, MED13, CREBBP, KDM6B,SMURF1, ADNP, CACNA1G, MYT1L, KIF13B, GRIA2, CHM, and KCNK9)." (PMID 38572415, 2024). "The phenotypic follow-up of cases of neurodevelopmental disorders has allowed to explore specific clinical phenotypes in a genotype-first manner, such as in the case of genes such as DYRK1A and activity-dependent neuroprotective protein (ADNP)." (PMID 35740400, 2022).
neurodegenerative disease (7 papers, 2015 to 2025). A disorder of the central nervous system characterized by gradual and progressive loss of neural tissue and neurologic function. "For example, the NAP peptide (NAPVSIPQ), derived from the activity-dependent neuroprotective protein (ADNP), has shown efficacy in in vitro as well as in vivo models of neurodegenerative diseases." (PMID 25996618, 2015). "Recently identified ADNP interactions with SHANK3 and SIRT1 may provide critical new targets for understanding the role that ADNP plays in neuropsychiatric, neurodevelopmental, and neurodegenerative disease." (PMID 35909451, 2022). "NAP, an octapeptide derived from activity-dependent neuroprotective protein (ADNP), attenuates Aβ-induced impairments in spatial memory and synaptic plasticity, offering promise as a therapeutic candidate for neurodegenerative diseases like AD." (PMID 40180804, 2025). "Activity-dependent neuroprotective protein (ADNP) gene is located in a chromosomal region, 20q12 as a component of the ChAHP (CHD4-ADNP-HP1) complex, with certain functions in neurodegenerative diseases and tumors." (PMID 37525242, 2023). "Therefore, therapeutic overexpression or CNS administration of these ADNP- or VGF-derived peptides have the potential to prevent the progression of comorbid neuropsychiatric and neurodegenerative diseases." (PMID 35909451, 2022).
infection (4 papers, 2017 to 2024). The state of being infected such as from the introduction of a foreign agent such as serum, vaccine, antigenic substance or organism. "In this study, ADNP was processed or degraded during infection: western blotting experiments showed ADNP at a molecular weight of 150 kDa together with discrete band signals at lower molecular weights." (PMID 38926592, 2024). "The interaction between Lpro and activity-dependent neuroprotective protein (ADNP) is crucial in the process of infection and promotes FMDV replication by inhibiting the expression of IFN and IFN stimulated gene (ISG)." (PMID 32899635, 2020). "RUVBL2, ADNP, SF3A2, CDK2, PRKDC, and NONO were particularly interesting as the increase in acetylation following SIRT2 inhibition temporally aligned with the time point of maximal interaction with SIRT2 during infection." (PMID 37916830, 2023).
neurological disorders (4 papers, 2017 to 2023). "It is an eight-amino-acid peptide derived from activity dependent neuroprotective protein (ADNP), was shown to have a brain bioavailability and neuroprotective effects in a wide variety of neurological disorders." (PMID 28052034, 2017).
heart diseases (1 paper, 2020). "As ADNP was linked before to heart development in mice and in humans, our current data may also imply sex-dependent ADNP effects in adult/aging heart diseases." (PMID 33086621, 2020).
myopathy (1 paper, 2020). A disease of the muscle in which the muscle fibers do not function properly. "We thus hypothesized that ADNP is deregulated in versatile myopathies and that local ADNP muscle deficiency results in myopathy, treatable by the ADNP fragment NAP." (PMID 33086621, 2020).
ADNP also shares sentences with these, for which no sentence is quoted: brain disorder (3 papers); epilepsy (3); glioblastoma multiforme (3); BAFopathies (2); Coffin-Siris syndrome (2); depression (2); mental disorder (2); Parkinson disease (2); progressive supranuclear palsy (2); adenoma (1); adult-onset Still disease (1); allergic asthma (1); amyotrophic lateral sclerosis (1); aneurysm (1); Astigmatism (1); Autoimmunity (1); Barrett esophagus (1); Becker muscular dystrophy (1); bipolar disorder (1); brain injury (1); breast carcinoma (1); Cerebral ischemia (1); CHARGE syndrome (1); chronic obstructive pulmonary disease (1); colon adenocarcinoma (1); congenital disorder of glycosylation (1); convergent strabismus (1); Cornelia de Lange syndrome (1); development (1); Down syndrome (1).
A further 39 diseases each share a sentence with ADNP in 1 paper.